IGF2BP2 (insulin like growth factor 2 mRNA binding protein 2)
Diseases named in the same sentence as IGF2BP2 in open-access papers (continued):
Sharing a sentence is not in itself a finding about the gene and the disease.
papillary thyroid cancer (7 papers, 2021 to 2025). "For example, in papillary thyroid cancer, IGF2BP2 increases the translational efficiency of erb-b2 receptor tyrosine kinase 2 (ERBB2) by binding to m6A motifs in its coding sequence (CDS), thereby conferring resistance to tyrosine kinase inhibitors." (PMID 39596216, 2024). "Similarly, the translational regulation of pancreatic and duodenal homeobox 1 (PDX1) in pancreatic β cells and ERBB2 in radioiodine-refractory papillary thyroid cancer also relies on IGF2BP2’s recognition of m6A methylation." (PMID 39596216, 2024). "IGF2BP2 recognizes and upregulates m6A-modified Apolipoprotein E (APOE), promoting glycolysis and tumor growth in papillary thyroid cancer." (PMID 39596216, 2024). "In papillary thyroid cancer, FTO acts as a tumor suppressor via suppress glycolysis and cell growth through IGF2BP2-mediated m6A modification." (PMID 36765416, 2023). "Moreover, IGF2BP2 recognizes and upregulates m6A-decorated Apolipoprotein E (APOE) to promote glycolysis and tumor growth in papillary thyroid cancer." (PMID 37554271, 2023).
diabetic nephropathy (6 papers, 2021 to 2025). "For European, Czech and Swedish populations, IGF2BP2 polymorphism has been associated with diabetic nephropathy in male patients with type 1 diabetes (T1D)." (PMID 33568150, 2021). "METTL3 targets TUG1/PGC-1α and ameliorates mitochondrial dysfunction in diabetic nephropathy in an IGF2BP2-dependent manner." (PMID 40685567, 2025). "Similarly, Airn protects against diabetic nephropathy (DN) by interacting with IGF2BP2 mRNA to promote the translation of proteins like IGF2 and LAMB2, maintaining podocyte viability and glomerular barrier function." (PMID 40141058, 2025). "A study showed that IGF2BP2 and IGF2 might have genetic effects in diabetes and diabetic nephropathy." (PMID 35597446, 2022).
melanoma (6 papers, 2021 to 2025). A malignant, usually aggressive tumor composed of atypical, neoplastic melanocytes. "Knockout experiments using CRISPR/Cas9 in mouse melanoma models showed that the loss of IGF2BP2 led to increased expression of MHC class I molecules, increasing cells’ ability to promote intracellular IFN-γ expression in syngeneic T-lymphocytes." (PMID 40141058, 2025). "A recent study confirmed the role of IGF2BP2 in melanoma development through the MSC-AS1/miR-302a-3p/IGF2BP2/LEF1 axis." (PMID 40211852, 2025). "In our retrospective analysis of human melanoma patients who received immunotherapy, high levels of IGF2BP1 and IGF2BP3, but not IGF2BP2, were associated with poor clinical outcomes." (PMID 37503349, 2023).
nasopharyngeal carcinoma (6 papers, 2020 to 2025). A carcinoma arising from the nasopharyngeal epithelium. "It has been uncovered that WTAP mediates m6A modification of lncRNA DIAPH1-AS1 and paves the way for the function of IGF2BP2 to increase the stability of lncRNA in nasopharyngeal carcinoma (NPC)." (PMID 38075202, 2024). "In nasopharyngeal carcinoma (NPC), METTL3-mediated m6A modification was enriched in TRIM11 mRNA and stabilized it depending on IGF2BP2." (PMID 36810281, 2023).
acute lymphoblastic leukemia (5 papers, 2022 to 2025). Leukemia with an acute onset, characterized by the presence of lymphoblasts in the bone marrow and the peripheral blood. "IGF2BP2 is highly expressed in T-cell acute lymphoblastic leukemia (T-ALL), and directly binds to the T-ALL oncogene NOTCH1 in an m6A-dependent manner, thereby stabilizing its mRNA and promoting tumorigenesis." (PMID 40823087, 2025). "Another paper explores targeting IGF2BP2 in T-cell acute lymphoblastic leukemia (T-ALL), revealing its role in promoting cell proliferation and impairing chemotherapy sensitivity by stabilizing NOTCH1 mRNA." (PMID 39456596, 2024). "In T-cell acute lymphoblastic leukemia (T-ALL), IGF2BP2 is highly expressed." (PMID 39295872, 2024). "Compared with other lymphoblastic leukemia cell lines, such as B-cell acute lymphoblastic leukemia (B-ALL), and chronic lymphoblastic leukemia (CLL), IGF2BP2 was the most highly expressed in T-cell acute lymphoblastic leukemia (T-ALL) among 14 human lymphoblastic leukemia cell lines." (PMID 35915142, 2022). "IGF2BP2 can directly bind to NOTCH1 and stabilize NOTCH1 mRNA expression in an m6A dependent manner, and the widespread expression of NOTCH1 may be closely linked to the presence of T-cell acute lymphoblastic leukemia (T-ALL)." (PMID 38711100, 2024).
head and neck cancer (5 papers, 2021 to 2025). A primary or metastatic malignant neoplasm affecting the head and neck. "In this study, we showed that IGF2BP2 was upregulated in head and neck cancer, and high levels of IGF2BP2 were associated with poor survival." (PMID 38250159, 2024). "Subsequently, in the comparison between head and neck cancer samples and normal tissues, a prominently higher expression of m6A regulators, such as IGF2BP2, was found in cancer samples." (PMID 35198565, 2021).
rhabdomyosarcoma (5 papers, 2015 to 2021). A rare aggressive malignant mesenchymal neoplasm arising from skeletal muscle. "Knockdown of HGMA2 in embryonic rhabdomyosarcoma cells resulted in severe downregulation of IGF2BP2 and knockdown of either HGMA2 or IGF2BP2 led to reduced protein levels encoded by the neuroblastoma RAS viral (v-ras) oncogene homolog (NRAS)." (PMID 25923053, 2015). "Previous study has proved that IGF2BP2 could stabilize multiple mRNAs and promoted embryonic rhabdomyosarcoma." (PMID 31682716, 2020). "IGF2BP2 has been reported to stabilize multiple mRNAs and promoted embryonic rhabdomyosarcoma." (PMID 31682716, 2020).
Sepsis (5 papers, 2022 to 2025). Sepsis is defined as life-threatening organ dysfunction caused by a dysregulated host response to infection. "For instance, the upregulation of circEXOC5 exacerbated sepsis-induced acute lung injury (ALI) by stimulating ferroptosis through insulin-like growth factor-2 mRNA-binding proteins 2 (IGF2BP2) recruitment for degrading activating transcription factor 3 (ATF3) mRNA." (PMID 39769377, 2024). "For sepsis, we found that PLCG2 was upregulated in immune cells during sepsis compared to healthy individuals, BCL6 was upregulated in Pre-B cells (CD34−) during sepsis, and IGF2BP2 was upregulated in GMP cells." (PMID 38167131, 2024).
Alzheimer disease (4 papers, 2021 to 2025). A progressive, neurodegenerative disease characterized by loss of function and death of nerve cells in several areas of the brain leading to loss of cognitive function such as memory and language. "This study first elucidates the pathogenic role of IGF2BP2 in Alzheimer’s disease." (PMID 34705667, 2021). "After compared between Alzheimer’s and normal brain samples, and between IGF2BP2- high and IGF2BP2- low subgroups of Alzheimer’s patients, we took the shared differentially expressed genes as the relevant gene sets of IGF2PB2 affecting Alzheimer’s disease occurrence for subsequent analysis." (PMID 34705667, 2021).
gestational diabetes (4 papers, 2020 to 2024). Carbohydrate intolerance first diagnosed during pregnancy. "Most of the studies of IGF2BP2 are focused on gestational diabetes, but a global meta‐analysis confers an association with T2DM both for Caucasians and for Indian populations." (PMID 32578971, 2020). "Moreover, IGF2BP2 rs4402960 is strongly associated with the development of gestational diabetes mellitus (GDM), besides being a potential diagnostic marker for GDM as well." (PMID 33568150, 2021).
hypopharyngeal carcinoma (4 papers, 2021 to 2024). Carcinoma, predominantly squamous cell, arising from the epithelial cells of the hypopharynx. "A recent study suggested that IGF2BP2 can combine with PD-L1 to promote the proliferation and inhibit the apoptosis of hypopharyngeal carcinoma cells through the PD-1/PD-L1 axis." (PMID 35299748, 2022). "The interplay between PD-L1 and insulin-like growth factor 2 mRNA binding protein 2 (IGF2BP2) in hypopharyngeal carcinoma has also been reported in the literature." (PMID 34968160, 2022). "A tumor-bearing nude model of hypopharyngeal carcinoma was constructed to evaluate the effect of a PD-L1 inhibitor and IGF2BP2 knockdown on hypopharyngeal carcinoma in vivo." (PMID 34608837, 2021). "IGF2BP2 expression was significantly upregulated in hypopharyngeal carcinoma cell lines compared with that in the normal human nasopharyngeal epithelial cell line, NP69SV40T." (PMID 34608837, 2021). "In this study, it was shown that IGF2BP2 expression was also elevated in the tissues of patients with hypopharyngeal carcinoma, indicating its potential role in hypopharyngeal carcinoma." (PMID 34608837, 2021). "In the present study, the roles of IGF2BP2 and PD-1/PD-L1 in hypopharyngeal carcinoma were investigated." (PMID 34608837, 2021). "The findings of the present study demonstrated that IGF2BP2 together with PD-1/PD-L1 may serve as effective biomarkers for the diagnosis and prognosis of hypopharyngeal carcinoma." (PMID 34608837, 2021). "So, the role of IGF2BP2 and PD-L1 in hypopharyngeal carcinoma was assessed." (PMID 34608837, 2021). "In conclusion, the results in the present study revealed that inhibition of IGF2BP2 might be a potentially relevant method for treating hypopharyngeal carcinoma, and the effects might be mediated via inhibition of the PD-1/PD-L1 axis." (PMID 34608837, 2021). "Additionally, the protein expression levels of IGF2BP2 were also higher in the hypopharyngeal cancer tissues." (PMID 34608837, 2021). "Taken together, these results confirmed that PD-1/PD-L1 and IGF2BP2 expression is increased in hypopharyngeal cancer, and may serve as a therapeutic target for management of hypopharyngeal cancer." (PMID 34608837, 2021). "Therefore, IGF2BP2 expression was knocked down in FaDu cells, and this resulted in reduced cell proliferation and increased apoptosis, suggesting its inhibitory effect on hypopharyngeal carcinoma." (PMID 34608837, 2021). "Furthermore, inhibition of IGF2BP2 and/or PD-L1 function may be a novel approach to the management of hypopharyngeal carcinoma." (PMID 34608837, 2021).
leiomyoma (4 papers, 2019 to 2023). A well-circumscribed benign smooth muscle neoplasm characterized by the presence of spindle cells with cigar-shaped nuclei, interlacing fascicles, and a whorled pattern. "In particular, suppression of the signaling pathway associated with the activation of the insulin-like growth factor IGF2BP2 gene is promising for the treatment of fibroids with overexpression of the HMGA2 gene." (PMID 31817606, 2019). "In leiomyomas, HMGA2 overexpression up-regulated IGF2BP2 and pAKT, which played an important role in the IGF2BP2-mediated pAKT activity in angiogenesis." (PMID 36281789, 2022).
metabolic syndrome (4 papers, 2011 to 2025). A cluster of metabolic risk factors for CARDIOVASCULAR DISEASES and TYPE 2 DIABETES MELLITUS. "Recent studies have identified that several genetic loci traditionally associated with T2D, such as TCF7L2, IGF2BP2, and FTO, may also influence IR in individuals with T1D, particularly in those with a long disease course or features of metabolic syndrome." (PMID 41019343, 2025). "The ADIPOQ gene is located nearby the IGF2BP2 (insulin-like growth factor 2 mRNA-binding protein 2) and AOMS1 (abdominal obesity-metabolic syndrome QTL 1) genes on chromosome 3q27 (based on Ensembl database)." (PMID 21251282, 2011).
osteoporosis (4 papers, 2024 to 2026). A condition of reduced bone mass, with decreased cortical thickness and a decrease in the number and size of the trabeculae of cancellous bone (but normal chemical composition), resulting in increased fracture incidence. "In another osteoporosis animal model, IGF2BP2 expression increased in aging osteoblasts under mechanical stress and H2O2 exposure, which promotes osteoblast senescence by improving the stability of Slc1a5 mRNA and inhibiting cell cycle progression." (PMID 40430096, 2025). "Our previous work identified IGF2BP2 dysregulation in osteoporosis." (PMID 41362747, 2026).
sarcoma (4 papers, 2018 to 2022). A usually aggressive malignant neoplasm of the soft tissue or bone. "Several lines of evidence support potential roles of IGF2BP2 in sarcomas." (PMID 29736175, 2018). "The HMGA2-driven IGF2BP2 expression is fundamental for the stability of NRAS mRNA and proteins, suggesting the importance of the HMGA-IGF2BP2 axis in different sarcomas." (PMID 29736175, 2018). "The expression levels of Cbl-like 1 (CBLL1) and IGF2BP2 in normal and sarcoma tissues were not statistically significant." (PMID 34979500, 2022).
T-cell acute lymphoblastic leukemia (4 papers, 2022 to 2025). Acute lymphoblastic leukemia of T-cell origin. "In T-cell acute lymphoblastic leukemia (T-ALL), IGF2BP2 binds to the oncogene NOTCH1 via an m6A-dependent mechanism and contributes to leukemogenesis." (PMID 40332203, 2025).
cardiomyopathies (3 papers, 2023 to 2025). "Taken together, these experiments indicate that various types of stress that lead to cardiomyopathies and heart failure upregulate IGF2BP2 in the heart." (PMID 38052926, 2023). "Here we demonstrate the involvement of IGF2BP2 in response to cardiac stress and in the development of cardiomyopathies." (PMID 38052926, 2023). "It is tempting to speculate that increased m6A RNA methylation could lead to elevated RNA binding by IGF2BP2, facilitating its role in mediating cardiomyopathies." (PMID 38052926, 2023).
colitis (3 papers, 2021 to 2025). Inflammation of the colon. "After 7 d 2.5% DSS administration, IGF2BP2–/– mice displayed more severe colitis compare with WT mice, associated with faster rate of body weight loss, higher disease activity index (DAI) and tinier colon length." (PMID 34258163, 2021). "In the DSS induced experimental acute colitis mice model, the IGF2BP2 deficient mice exhibited an enhanced colitis phenotype characterized by more body weight loss, shorter colon length, more severe epithelial damage, and higher inflammatory cytokines production." (PMID 34258163, 2021). "To confirm the influence of IGF2BP2 on intestinal mucosal barrier integrity in the context of DSS-induced colitis, we generated a murine model of UC by administering DSS to trigger colitis manifestations." (PMID 40241612, 2025). "Myeloid depletion of IGF2BP2 promotes dextran sulfate sodium induced colitis development while alleviates cockroach extract induced pulmonary allergic inflammation." (PMID 34258163, 2021). "Then, we evaluated the impact of IGF2BP2 in dextran sulfate sodium (DSS)‐induced colitis mice model." (PMID 34258163, 2021). "Here, it is observed that insulin‐like growth factor 2 messenger RNA (mRNA)‐binding protein 2 (IGF2BP2)‐deleted macrophages exhibit enhanced M1 phenotype and promote dextran sulfate sodium induced colitis development." (PMID 34258163, 2021). "Additionally, the evidence highlights the significant involvement of IGF2BP2 in macrophage activation during the development of colitis induced by DSS." (PMID 38830900, 2024). "Depletion of IGF2BP2 resulted in an increase in the M1-like macrophage phenotype and promoted the development of DSS-induced colitis." (PMID 38830900, 2024). "Defect of IGF2BP2 promoted M1 response, leading to enhancing DSS induced experimental colitis development, but impaired M2 activation through stabilizing TSC1 and PPARγ mRNA." (PMID 34258163, 2021).
esophagogastric junction adenocarcinoma (3 papers, 2019 to 2021). "In addition, SNPs of IGF2BP2 and IGF2BP3 has been proved to promote the lymph node metastasis of esophagogastric junction adenocarcinoma." (PMID 32514248, 2020).
Ewing sarcoma (3 papers, 2019 to 2022). A small round cell tumor that lacks morphologic, immunohistochemical, and electron microscopic evidence of neuroectodermal differentiation. "HMGA2, IGF2BP2, IGF2BP3, and IGF2 were confirmed to be significantly overexpressed in CDS-derived cell lines compared with Ewing sarcoma–derived cell lines." (PMID 34903601, 2022). "qRT-PCR confirmed that CDS specimens exhibited significantly elevated expression of HMGA2, IGF2BP2, IGF2BP3, and IGF2, but not HMGA1, compared with Ewing sarcoma specimens." (PMID 34903601, 2022).
hepatoblastoma (3 papers, 2022 to 2025). Hepatoblastoma (HB) is a malignant hepatic tumor and is the most common pediatric liver cancer. "Inhibition of miR-216b profoundly decreased the proliferation of HCC SMMC-7721 cells by regulating insulin-like growth factor 2 mRNA-binding protein 2, while overexpression of miR-216b inhibited replication of hepatitis B virus and proliferation of human hepatoblastoma HepG2.215 cells." (PMID 35711801, 2022). "As an m6A “reader”, IGF2BP2 has been shown to enhance the stability of SLC7A11 mRNA through m6A modification, thereby conferring ferroptosis resistance to hepatoblastomas." (PMID 39731162, 2024).
Hypertension (3 papers, 2014 to 2022). The presence of chronic increased pressure in the systemic arterial system. "Genotype TT of SNP rs4402960 within the gene IGF2BP2 was associated with overweight (odds ratio (OR) = 0.479, 95% confidence interval (CI): 0.316-0.724, p = 0.001) and genotype CA of SNP rs1801131 within the gene MTHFR was associated with hypertension (OR = 1.560, 95% CI: 1.194–2.240, p = 0.001)." (PMID 24959828, 2014).
injury (3 papers, 2022 to 2025). Damage inflicted on the body as the direct or indirect result of an external force, with or without disruption of structural continuity. "Other research indicates that IGF2BP2 plays a regulatory role in the pathological mechanisms of Lung ischemia–reperfusion injury (LIRI), Hemoglobin H-Constant Spring disease (HbH-CS), Autoimmune inflammation, and other diseases." (PMID 35129592, 2022). "Beyond the IGF2BP2/SOX11 axis identified in our study, other mechanisms may also play a role in regulating OM‐MSC neuronal differentiation and the repair of ICH‐induced brain injury." (PMID 40485217, 2025).
ischemic stroke (3 papers, 2022 to 2025). A stroke disorder caused by obstruction of blood flow to the brain, due to thrombotic (local blood clot formation) or embolic (due to a blood clot or other material traveling from another site) event. "One study investigated the role of trimethylamine N‐oxide in ischemic stroke and found it could promote the activation of the NLRP3 inflammasome in microglia through the FTO/IGF2BP2 pathway, thereby aggravating neurological injury in ischemic stroke." (PMID 39161158, 2024).
laryngeal squamous cell carcinoma (3 papers, 2023 to 2024). A squamous cell carcinoma that arises from the larynx. "Other researchers also found that IGF2BP2 and HNRNPC can mediate the transport of circCDK1 and circZBTB44 into the cytoplasm in laryngeal squamous cell carcinoma and renal cell carcinomas, respectively." (PMID 39075555, 2024).
liposarcoma (3 papers, 2018 to 2022). A usually painless malignant tumor that arises from adipose tissue. "A higher level of IGF2BP2 was found in well-differentiated liposarcoma, in comparison with myxoid liposarcoma, suggesting that IGF2BP2 may potentially be used to distinguish myxoid liposarcoma from the well-differentiated liposarcoma." (PMID 29736175, 2018).